MET (MET proto-oncogene, receptor tyrosine kinase)
Diseases named in the same sentence as MET in open-access papers (continued):
Sharing a sentence is not in itself a finding about the gene and the disease.
cutaneous melanoma (6 papers, 2013 to 2023). A primary melanoma arising from atypical melanocytes in the skin. "Our study suggests that high expression of MACC1 or both MACC1 and MET is associated with metastasis of cutaneous melanoma." (PMID 37496665, 2023). "In summary, our data suggest that MACC1 may be a potentially useful biomarker associated with progression of invasion and metastasis in cutaneous melanoma, especially in conjunction with high expression of MET protein." (PMID 37496665, 2023). "The receptor for HGF, named c-MET (MET), has been found in uveal melanoma tumors and cells previously and our own work on MET in N-Ras mutated cutaneous melanoma has prompted us to explore this system in more detail." (PMID 24551032, 2014). "Further, through the GEPIA database, in cutaneous melanoma, we examined the association between the ERBBs and 31 genes were close to each other and frequently altered and observed that all the genes except KIT, ALK, NTRK1, FGFR4, and MET were affected by the changes of some ERBB family members." (PMID 33732282, 2021).
dysplasia (6 papers, 2014 to 2025). A usually neoplastic transformation of the cell, associated with altered architectural tissue patterns. "Interestingly, MET expression correlates with esophageal metaplasia–dysplasia–adenocarcinoma transformation, with a percentage of MET amplification in about 9% of cases." (PMID 28548075, 2014). "In contrast, mutations in JAK3 (Janus kinase 3), MET, and FBXW7 (F-Box and WD repeat domain containing 7) were found only in non-progressing dysplasia, but absent in progressing dysplasia and LSCC cases." (PMID 35406495, 2022).
GEJ adenocarcinoma (6 papers, 2013 to 2024). "Outlier expression of the targetable oncogene MET was detected in a patient with GEJ adenocarcinoma and of NTRK1 in a patient with medullary colon cancer, respectively." (PMID 34385467, 2021). "Meanwhile, recent study has demonstrated that 2% of patients (10/489) with esophagogastric adenocarcinoma harbored MET amplification and two of four patients with MET-amplified tumors treated with a MET inhibitor experienced tumor shrinkage." (PMID 23426935, 2013). "Recently, two large-scale randomized phase III trials (RILOMET-1 study: rilotumumab, MetGastric study: onarutuzumab) evaluated the efficacy of adding HGF/MET inhibitor to first-line chemotherapy in MET-positive patients with unresectable gastric or GEJ adenocarcinoma." (PMID 26716644, 2016). "Ramucirumab monotherapy or in combination with paclitaxel is a second-line treatment option for patients with advanced gastric or gastroesophageal junction adenocarcinoma (with or without hepatocyte growth factor receptor [MET]-positive tumors)." (PMID 38339049, 2024).
hereditary leiomyomatosis (6 papers, 2014 to 2024). "Germ line met proto-oncogene (MET) and FH alterations are observed in the hereditary form of papillary 1 and in the hereditary leiomyomatosis (type 2), respectively." (PMID 25274276, 2014). "Besides MET mutation associated HPRC, another form of hereditary pRCC is found in the autosomal dominant syndrome, hereditary leiomyomatosis, and renal cell carcinoma (HLRCC)." (PMID 26448938, 2015).
intrahepatic cholangiocarcinoma (6 papers, 2021 to 2025). A carcinoma that arises from the intrahepatic bile duct epithelium in any site of the intrahepatic biliary tree. "Since MET fusions have been previously targeted in intrahepatic cholangiocarcinoma case studies, the MTB decision was to start the patient on MET inhibitor crizotinib." (PMID 38833619, 2025). "During the development of intrahepatic cholangiocarcinoma, activated HSCs transition into myofibroblasts (myCAFs) and inflammatory CAFs (iCAFs), which promote the progression of intrahepatic cholangiocarcinoma through the Has2/HA pathway and HGF/MET pathway, respectively." (PMID 41214328, 2025).
laryngeal carcinoma (6 papers, 2015 to 2023). Carcinoma that arises from the laryngeal epithelium. "Analogous phenomenon was noticed by Lee and co-workers who showed that ME22S (a novel EGFR/MET bispecific antibody) significantly inhibited HGF-stimulated migration and invasion of laryngeal carcinoma cells." (PMID 31649529, 2019).
ovarian tumors (6 papers, 2011 to 2024). "Activation of the HGF/c-MET axis has been demonstrated in certain ovarian tumours, and been found to be associated with decreased overall survival, suggesting its potential as a therapeutic target." (PMID 26138303, 2015). "For example, in ovarian tumors, AXL dimerizes with MET, EGFR, and HER2, leading to sustained ERK activation." (PMID 32245042, 2020). "Receptor EGFR, ERBB2, MET, and AXL were strongly co-activated in most primary ovarian tumors." (PMID 21962244, 2011).
pancreatic neuroendocrine tumor (6 papers, 2013 to 2023). Pancreatic endocrine tumor, also known as pancreatic neuroendocrine tumor (PNET), describes a group of endocrine tumors originating in the pancreas that are usually indolent and benign, but may have the potential to be malignant. "Efficacy of simultaneous inhibition of VEGFR2 and MET was also shown in pancreatic neuroendocrine tumors, with decreased tumor growth and reduction in invasion and metastasis." (PMID 24205338, 2013). "The efficacy of combining MET and VEGF inhibitors showed beneficial effect in murine GBM overexpressing MET and in pancreatic neuroendocrine tumors." (PMID 29270405, 2017). "Preclinical evidence clarified that the dual blockade of MET and VEGF signaling in RIP-Tag2 mice may reduce the invasive and metastatic capabilities of pancreatic NETs (paNET) cells with a synergistic effect, thereby providing a strong rationale for using CAB in this setting." (PMID 37855330, 2023).
rectal cancer (6 papers, 2015 to 2026). A primary or metastatic malignant neoplasm that affects the rectum. "Chromosome 7 harbors many interesting genes, including druggable targets such as the oncogenes EGFR, BRAF and MET, but at present their relation to the retention of chromosome 7 and the development of local recurrent disease in rectal cancer is unclear." (PMID 26048403, 2015). "They demonstrated that c-MET protein overexpression is related to tumour recurrence and is associated with worse prognosis and suggested that inhibition of c-MET is a potential new strategy for reduction of distant recurrence of rectal carcinoma after preoperative chemotherapy." (PMID 26459369, 2015).
steatosis (6 papers, 2012 to 2024). Increased lipid within the cytoplasm of cells. "Studying the role of c-MET in murine NASH models revealed that hepatocyte specific c-Met knockout mice (c-MetΔhepa) exhibited increased steatosis and liver infiltration upon a methionine-choline deficient (MCD) diet compared to wild type controls (c-MetloxP/loxP)." (PMID 35087852, 2021).
thyroid (6 papers, 2011 to 2025). "Although PTC is the most common thyroid malignancy in both pediatric and adult populations, established molecular differences—such as the predominance of BRAFV600E and RAS mutations in adults versus RET, NTRK, ALK, and MET alterations in children—may result in cytomorphological differences." (PMID 41462793, 2025). "MET, EML4, and ALK fusions also clustered with similar variables, along with the family history of thyroid diseases in general." (PMID 39409115, 2024). "Thyroid disease in the patient’s family, Hashimoto’s disease, and hypothyroidism, as well as the type of thyroidectomy, the need for indicating RAI, and smaller tumor size, clustered quite well with gene fusions related to RET, CCDC6, MET, EML4, and ALK." (PMID 39409115, 2024).
acute kidney injury (5 papers, 2015 to 2025). Sudden and sustained deterioration of the kidney function characterized by decreased glomerular filtration rate, increased serum creatinine or oliguria. "In another clinical trial with locally advanced or metastatic, MET-amplified, EGFR mutation-positive NSCLC, a case of acute renal failure was found in patients treated with osimertinib plus savolitinib." (PMID 39026680, 2024).
alveolar soft part sarcoma (5 papers, 2012 to 2025). An alveolar soft part sarcoma occurring in adults. "Tsuda and colleagues reported that gene fusions involving TFE3 can activate MET signaling; hence, they proposed that MET inhibitors may be potential candidates for managing alveolar soft part sarcoma." (PMID 40563544, 2025). "Alveolar soft part sarcoma (ASPS) often carries a translocation between ASPSCR1 and TFE3 genes, resulting in a fusion protein that transcriptionally upregulates MET." (PMID 37213274, 2023).
biliary tract cancer (5 papers, 2013 to 2025). "A retrospective study conducted by Xu et al15 revealed that MET rearrangement was seen in only 1.1% of patients with biliary tract cancer (BTC)." (PMID 39658086, 2025). "Summary of published cases of biliary tract cancers with alterations involving MET and targeted treatment with MET inhibitors." (PMID 39356253, 2024). "The use of MET inhibitor in combination with gemcitabine achieved a 46% of SD and 20% of PR in patients with MET overexpression (about 34% seen in biliary tract cancers) in a small phase 1 trail." (PMID 36199981, 2022).
hearing loss (5 papers, 2019 to 2025). "Specifically, non-coding mutations of HGF are associated with non-syndromic hearing loss, autosomal recessive deafness-39 (DFNB39), while a mutation in MET is associated with human DFNB97 hearing loss." (PMID 31185063, 2019). "For example, a recent study has demonstrated that loxhd-1 mutation in the inner hair cell does not affect the structural integrity of the hair cell bundle but rather prevents the activation of MET (mechanoelectrical transducer) channels, thereby contributing to progressive hearing loss in mice." (PMID 40463242, 2025). "More and more studies have shown that defects in the HGF/c-MET signaling pathway can lead to the inability of melanocytes to successfully integrate the intermediate cell layer, resulting in hearing impairment." (PMID 41411333, 2025). "Interestingly, a homozygous missense mutation (Phe841Val) in MET was reported in a Pakistani family with hearing impairment; however, no such phenotype was detected in any affected individuals in the current study." (PMID 34440456, 2021).
lymphedema (5 papers, 2014 to 2025). Excess fluid collection in tissues, causing swelling. "GJA4 was chosen because it encodes Cx37; other studies have already described that two genes (GJC2 encoding connexin 47 and MET gene) also involved in junction formation have mutations associated with the predisposition to secondary lymphedema." (PMID 29470392, 2018). "Signaling pathways such as the RAS/MAPK pathway, the PI3K/AKT pathway, the TGF-β1 pathway, and the HGF/MET signaling pathway have been confirmed to play important roles in the development and progression of lymphedema." (PMID 40766782, 2025). "Regulatory molecules of the HGF/MET signaling pathway are equally able to participate in the progression of lymphedema." (PMID 40766782, 2025). "The HGF/MET signaling pathway plays an important role in the pathogenesis of lymphedema, which is closely related to the interaction of RAS/M APK signaling and PI3K/AKT signaling." (PMID 40766782, 2025). "In recent years, new advances and breakthroughs have been made in signaling pathways, including RAS/MAPK, PI3K/AKT, VEGF-C/VEGFR-3, HGF/MET, and TGF-β1, which are important for understanding the pathogenesis and disease progression of lymphedema." (PMID 40766782, 2025).
meningioma (5 papers, 2021 to 2024). A generally slow growing tumor attached to the dura mater. "Expressions of HGF and c-MET have been associated with aggressive meningiomas." (PMID 34408780, 2021). "We investigated the association between curcumin, EMT, and HGF/c-MET in meningioma cells." (PMID 34408780, 2021). "Compared to WHO grade I meningioma tissues, expression levels of HGF and c-MET were found to be elevated in WHO grade III (malignant) meningioma tissues." (PMID 34408780, 2021). "To detect the expression of HGF and c-MET in meningioma, we performed immunohistochemistry and western blot assays." (PMID 34408780, 2021). "c-MET expression levels have been shown to be elevated in aggressive meningiomas, and curcumin inhibited the proliferation and migration of meningioma cells." (PMID 34408780, 2021). "Both HGF and c-MET were strongly positive in malignant meningioma tissues and weakly positive in benign meningioma tissues." (PMID 34408780, 2021). "We found that HGF and c-MET levels were upregulated in malignant meningioma clinical tissues, compared to benign meningioma clinical tissues, consistent with previous studies." (PMID 34408780, 2021). "The PI3K/Akt/mTOR pathway is one of the major signaling pathways downstream of c-MET activation and is associated with cell metastasis, invasion, and EMT of cancer cells, including meningioma cells." (PMID 34408780, 2021). "Moreover, carbozantinib also inhibits receptor tyrosine kinases AXL and c-MET, which have both previously been shown to demonstrate elevated expression in recurrent meningiomas." (PMID 36672431, 2023). "In addition, HGF and c-MET are overexpressed in meningioma and are predictive markers as well as targeted therapy molecules for meningioma." (PMID 34408780, 2021). "In addition, treatment of human malignant meningioma cells with the tyrosine protein kinase (c-MET) inhibitor (SU11274) or the phosphoinositide 3-kinase (PI3K) inhibitor (LY294002) suppressed HGF-induced migration and EMT." (PMID 34408780, 2021). "Alterations of other relevant genes involved in meningiomas such as gains of EGFR (found here in a primary RM case and other recurrent RM specimens) and gains of the MET gene (detected here also in one patient), appear to be infrequent in RM." (PMID 38785832, 2024). "Similarly, when comparing the amino acid profiles of patients with meningioma to the control group, the differences observed concerned endogenous amino acids (GLN, CIT, GABA, ORN, ASP) and exogenous amino acids (THR, MET, LYS, AAA, PHE, C-C, TYR)." (PMID 38067430, 2023). "To further investigate the effects of the PI3K/Akt/mTOR pathway on HGF-induced meningioma cells, we treated IOMM-Lee cells with a c-MET inhibitor (SU11274, 5 μmol/l) and a PI3K inhibitor (LY29400225, μmol/l), respectively, and then the proliferation, migration, invasion, and EMT were detected." (PMID 34408780, 2021).
PEComas (5 papers, 2020 to 2025). "TFE3-translocated PEComas are less responsive to mTOR inhibitors, and the low response rate is associated with MET pathway activation, which is one of the mechanisms of mTOR inhibitor resistance." (PMID 40989692, 2025). "In contrast, PEComas with TFE3 rearrangements, associated with MET pathway activation, tend to exhibit lower response rates to mTOR inhibitors." (PMID 40647483, 2025). "Recently, two molecular subgroups of PEComas were proposed: type 1, which responds to mTOR inhibitors, and type 2, which responds to c-MET inhibitors." (PMID 39026968, 2024). "Recently, a subdivision into two molecular subgroups of PEComas was proposed: type 1, responding to mTOR inhibitors and type 2 responding to c-MET inhibitors." (PMID 34680376, 2021). "Therefore, it has been proposed that PEComas can be subdivided into two molecular subgroups: type 1, which is responsive to mTOR inhibitors, and type 2, which is responsive to c-MET inhibitors." (PMID 40989692, 2025). "c-MET inhibitors may be more effective in TFE3-altered PEComas because TFE3 fusions increase MET signaling through transcriptional up-regulation." (PMID 39026968, 2024). "Therefore, c-MET inhibitors may be more effective in TFE3-altered PEComas." (PMID 40989692, 2025). "c-MET inhibitors could be more efficient in TFE3-altered PEComas, since TFE3 fusions activate MET signaling by transcriptional up-regulation." (PMID 34680376, 2021).
pneumonitis (5 papers, 2022 to 2025). An inflammatory process affecting the lung parenchyma. "The safety of treating a patient with a MET inhibitor after drug-induced pneumonitis by another MET inhibitor remains unclear." (PMID 36233109, 2022). "A recent retrospective cohort showed that six of seven patients who received MET inhibitors following ICI presented with an early grade ≥3 AE (4 transaminitis, 2 pneumonitis), leading to the permanent discontinuation of MET inhibitors in 3 of the six patients." (PMID 35491960, 2022).
seminoma (5 papers, 2018 to 2025). A radiosensitive malignant germ cell tumor found in the testis (especially undescended), and extragonadal sites (anterior mediastinum and pineal gland). "Some of our previous studies investigated the c-MET/HGF system involvement in non-seminoma cell malignant behavior." (PMID 37509533, 2023). "All together, these observations led us to further investigate the c-MET-triggered signal transduction pathway in non-seminoma cell malignant behavior." (PMID 33212946, 2020). "All together these observations lead us to deeper investigate the role of c-MET-triggered signal transduction in non-seminoma cell malignant behaviour." (PMID 30646583, 2019). "In a recent paper we found that, HGF is able to stimulate the malignant and aggressive behaviour of NT2D1 non-seminoma cells, and that this phenomenon depends on c-MET activation." (PMID 30646583, 2019). "In particular, we elucidated that the non-seminoma lesions express c-MET protein at higher level, compared with the seminoma ones." (PMID 30646583, 2019). "In the present study, we investigated the role of PI3K in the HGF-dependent and c-MET-activated malignant behavior of NT2D1 non-seminoma cells, studying the effects of PI3K inhibition on the already described biological responses to HGF (proliferation, migration, and invasion)." (PMID 33212946, 2020). "Moreover, the results herein reported strongly stimulates to investigate deeply, at proteomic level, the overexpression of HGF as well the over-activation of c-MET and c-Src in TGTCs biopsies with special focus on non-seminoma lesions." (PMID 30646583, 2019). "Interestingly, the immunohistochemical study of c-MET distribution in TGCTs confirm its presence in both seminoma and non-seminoma lesions with different patterns." (PMID 30159127, 2018). "We studied c-MET and HGF expression even in seminoma and non-seminoma derived cell lines (TCam-2, NCCIT, NT2D1), demonstrating that HGF is not expressed by all these cell lines." (PMID 37509533, 2023). "NSGCT showed higher levels of c-MET protein compared to GCNIS and seminoma." (PMID 40011822, 2025).
small cell carcinoma (5 papers, 2016 to 2025). A neuroendocrine carcinoma composed of small malignant cells which are often said to resemble "oat cells" under the microscope. "Other mechanisms include small cell carcinoma transformation, gene amplification of EGFR, ERBB2, and MET and additional mutations in PI3K, BRAF, and KRAS32–36." (PMID 33863951, 2021). "These include additional mutations in EGFR (40–60%) and mutations in PIK3CA (5%) and BRAF (1%), amplification of MET (5–10%) and ERBB2 (12%), phenotypic transformation such as to small cell carcinoma (3–14%) and the epithelial to mesenchymal transition." (PMID 27304188, 2016).
undifferentiated carcinoma (5 papers, 2015 to 2025). A usually aggressive malignant epithelial neoplasm composed of atypical cells which do not display evidence of glandular, squamous, or transitional cell differentiation. "MET amplification has been found to be significant in a series of ATC (5 out of 42 anaplastic carcinomas (11.9%) with 3.5 to 8.7 copy number gains)." (PMID 31040922, 2019).